PRKG1 (protein kinase cGMP-dependent 1)
Description:
Serine/threonine protein kinase that acts as a key mediator of the nitric oxide (NO)/cGMP signaling pathway. GMP binding activates PRKG1, which phosphorylates serines and threonines on many cellular proteins. Numerous protein targets for PRKG1 phosphorylation are implicated in modulating cellular calcium, but the contribution of each of these targets may vary substantially among cell types. Proteins that are phosphorylated by PRKG1 regulate platelet activation and adhesion, smooth muscle contraction, cardiac function, gene expression, feedback of the NO-signaling pathway, and other processes involved in several aspects of the CNS like axon guidance, hippocampal and cerebellar learning, circadian rhythm and nociception. Smooth muscle relaxation is mediated through lowering of intracellular free calcium, by desensitization of contractile proteins to calcium, and by decrease in the contractile state of smooth muscle or in platelet activation. Regulates intracellular calcium levels via several pathways: phosphorylates IRAG1 and inhibits IP3-induced Ca(2+) release from intracellular stores, phosphorylation of KCNMA1 (BKCa) channels decreases intracellular Ca(2+) levels, which leads to increased opening of this channel. PRKG1 phosphorylates the canonical transient receptor potential channel (TRPC) family which inactivates the associated inward calcium current. Another mode of action of NO/cGMP/PKGI signaling involves PKGI-mediated inactivation of the Ras homolog gene family member A (RhoA). Phosphorylation of RHOA by PRKG1 blocks the action of this protein in myriad processes: regulation of RHOA translocation; decreasing contraction; controlling vesicle trafficking, reduction of myosin light chain phosphorylation resulting in vasorelaxation. Activation of PRKG1 by NO signaling also alters gene expression in a number of tissues. In smooth muscle cells, increased cGMP and PRKG1 activity influence expression of smooth muscle-specific contractile proteins, levels of proteins in the NO/cGMP signaling pathway, down-regulation of the matrix proteins osteopontin and thrombospondin-1 to limit smooth muscle cell migration and phenotype. Regulates vasodilator-stimulated phosphoprotein (VASP) functions in platelets and smooth muscle.
Synonyms: cGK 1; cGK1; cGKI; PRKG1B; PRKGR1B; PGK; PKG; PKG1; AAT8; cGK; cGKI-BETA; cGKI-alpha
Tractability: Small molecule: a structure with a bound ligand is known; a high-quality ligand is known; it has a binding pocket of medium quality; it belongs to a druggable protein family. Antibody: its Gene Ontology location is reachable by antibodies, with high confidence. PROTAC: a small molecule that binds it is known.
Target class: Kinase; AGC protein kinase group; Enzyme; AGC protein kinase PKG family; Protein Kinase
Safety:
Unwanted effects reported when the protein is acted on. In parentheses: how it was acted on, where the effect was seen, and who reports it.
cardiac arrhythmia (cardiovascular system; source: Lamore et al. (2017))
heart disease (cardiovascular system; source: Force et al. (2011))
Gene: Protein-coding gene on chromosome 10 (50,990,888 to 52,298,423, forward strand). Ensembl gene ENSG00000185532.
Subcellular location: Cytoplasm
Subcellular location (Human Protein Atlas): Cytosol; Vesicles
Pathways (Reactome):
Disease: Maturation of DENV proteins
Hemostasis: cGMP effects
Immune System: Rap1 signalling
Signal Transduction: Ca2+ pathway
Gene Ontology:
Molecular function: calcium channel regulator activity; cGMP-dependent protein kinase activity; protein binding; protein kinase activity; ATP binding; cGMP binding; protein serine kinase activity; protein serine/threonine kinase activity
Biological process: negative regulation of platelet aggregation; negative regulation of vascular associated smooth muscle cell migration; negative regulation of vascular associated smooth muscle cell proliferation; regulation of vascular permeability; relaxation of vascular associated smooth muscle; bone growth; signal transduction; collateral sprouting; receptor guanylyl cyclase signaling pathway
Cellular component: cytoplasm; plasma membrane; cytosol; Golgi apparatus
Genetic constraint (gnomAD): Loss-of-function variants: 29 observed, 74.04 expected, observed/expected ratio (o/e) 0.39, 90% interval 0.29 to 0.53. The upper end of that interval is the gene's LOEUF score, 0.53, which puts it in group 2 of 6, group 1 being the genes least tolerant of losing a copy. Missense variants: 498 observed, 798.25 expected, observed/expected ratio (o/e) 0.62, 90% interval 0.58 to 0.67. Synonymous variants: 280 observed, 281.26 expected, observed/expected ratio (o/e) 1, 90% interval 0.9 to 1.1.
Gene-disease validity (ClinGen):
ClinGen rates the evidence that PRKG1 causes each of these diseases.
familial thoracic aortic aneurysm and aortic dissection (autosomal dominant): Strong. A rare genetic vascular disease characterized by the familial occurrence of thoracic aortic aneurysm, dissection or dilatation affecting one or more aortic segments (aortic root, ascending aorta, arch or descending aorta) in the absence of any other associated disease.
Homologues: Orthologues: chimpanzee PRKG1 (100% identical), macaque PRKG1 (100% identical), pig PRKG1 (99% identical), rat Prkg1 (99% identical), guinea pig PRKG1 (99% identical), rabbit PRKG1 (99% identical), dog PRKG1 (99% identical), tropical clawed frog prkg1 (95% identical), zebrafish prkg1b (94% identical), mouse Prkg1 (89% identical), Drosophila melanogaster CG12069 (19% identical), Drosophila melanogaster Pka-C2 (17% identical). Paralogues in human: PRKG2 (51% identical), PRKACB (23% identical), PRKACA (22% identical), PRKX (22% identical), PRKACG (21% identical).
Diseases named in the same sentence as PRKG1 in open-access papers:
PRKG1 is named in the same sentence as 167 diseases in open-access papers, as found by Europe PMC text mining. Sharing a sentence is not in itself a finding about the gene and the disease. The quoted sentences say what the papers report.
breast carcinoma (27 papers, 2010 to 2025). "On 10q21.1, rs1892368 is an intronic variant in PRKG1 (protein kinase cGMP-dependent 1) that was inversely associated with both DA and breast cancer risk (P = 4.8 × 10−7)." (PMID 33037222, 2020). "Alterations of PRKG1 have been implicated in the origin of clonal expansion of primary tumors from breast cancers, hepatocellular carcinomas and uterine leiomyomas." (PMID 20830292, 2010). "Five additional loci were newly associated with both DA and breast cancer risk in the same direction, identifying LMNB1, MKX, PRKG1, MRPL17, and SMIM25 as candidate genes for both DA and breast cancer risk." (PMID 33037222, 2020). "Initially, univariate Cox regression analysis revealed that 12 genes were associated with the prognosis of breast cancer, followed by LASSO analysis to derive a prognostic signature composed of 8 genes, including CERCAM, EMP1, SDC1, PRKG1, XG, TNN, WLS, and PDLIM4." (PMID 38728370, 2024).
heart failure (21 papers, 2013 to 2025). Inability of the heart to pump blood at an adequate rate to meet tissue metabolic requirements. "Involvement of the cGMP-PKG signaling pathway in the cardiac contractility makes the PRKG1 gene a possible candidate for heart failure in COVID-19 patients." (PMID 35794133, 2022).
malaria (21 papers, 2009 to 2025). Malaria is a serious and sometimes fatal disease caused by a parasite that commonly infects a certain type of mosquito which feeds on humans. "Genes with top scores encode for different malaria relevant functions such as regulation of inflammation (CSMD1), neural adhesion (CNTN4, PCSK5, CDH13, TMEM132), vascular epithelial development (FLT4), and protein kinases (PTPRT, PRKG1)." (PMID 34868193, 2021).
colon carcinoma (19 papers, 2007 to 2025). "However, suppression of PDE5 with antisense transcripts or PDE5 inhibitors promotes colon cancer cell apoptosis and inhibits growth, which is involving the activation of the cGMP/PRKG1 signaling pathway." (PMID 39139561, 2024). "Specifically, we targeted large genes PRKG1, NEGR1, and MAGI2 in fibroblast line UM-HF1 (HF1) and FHIT and WWOX in lymphoblastoid line GM12878 and colon cancer line HCT116 as model systems for replication stress-associated SV formation." (PMID 39505880, 2024).
Hypertension (14 papers, 2011 to 2025). The presence of chronic increased pressure in the systemic arterial system. "Lorena Citterio conducted a GWAS in a white population with mild hypertension and found that rs7897633 in PRKG1 was associated with DBP changes after acute salt loading." (PMID 34671380, 2021). "A genome-wide association study found that common genetic polymorphisms in human cGKI-1 gene (PRKG1) are significantly associated with enhanced diastolic blood pressure in response to an acute salt load in patients with hypertension." (PMID 26016544, 2015). "In this study a four-gene interaction model of association that includes PRKG1 was found to affect the risk for essential hypertension." (PMID 21573014, 2011). "In PRKG1 mutations, hypertension was found in over 70% of cases in a series." (PMID 33807627, 2021). "Several variants, including PRKG1 rs1904694, CYP4A11 rs1126742, and CYBA rs4673, demonstrated associations with increased hypertension susceptibility." (PMID 41573461, 2025). "Furthermore, global Prkg1-KO mice have a strongly reduced survival time and age-dependent systemic hypertension, in contrast to IRAG1-KO mice." (PMID 34064290, 2021). "Hypertension in a young patient with a TAA may point to a search of FBN-1, PRKG1 or other aorthopathy genes mutations." (PMID 33807627, 2021). "An intriguing aspect regarding hypertension in PRKG1 mutations is the fact that the gain-of-function of PKG1 should lead to SMC relaxation and hypotension; however, many patients including ours have hypertension instead, suggesting the involvement of other mechanisms." (PMID 33807627, 2021). "Hypertension was found in FBN1 gene mutations encoding fibrillin and in PRKG1 mutations." (PMID 33807627, 2021). "Four SNPs (PRKG1/rs1904694 and rs7897633, CYP4A11/rs1126742, and CYBA/rs4673) were still significantly associated after Bonferroni correction (P < 0.0007) adjusted for age, sex, fasting blood glucose, total cholesterol, salt-eating habit, physical activity, and hypertension." (PMID 34671380, 2021). "Last, but not least, other genes may contribute to hypertension in PRKG1 mutations." (PMID 33807627, 2021).
retinal degeneration (12 papers, 2021 to 2025). Degeneration of the retina. "Their expression in the retina was demonstrated and the correlation with retinal degeneration was shown in a CNGC loss-of-function mouse model in which the knock-out of Prkg1 led to sustained rod cell survival." (PMID 34208617, 2021). "PRKG1 deficiency does not prevent retinal degeneration in Pde6g-/- mice but does so in Cngb1-/- mice, even though cell death in both cases is caused by cGMP elevation." (PMID 38350962, 2024). "Finally, dual inhibition of CNG channel activity and PKG signaling may achieve the best effect, as the knockout of Prkg1 was found to slow retinal degeneration in Cngb1−/− but not in Pde6g−/− mouse models." (PMID 40631959, 2025).
pulmonary hypertension (11 papers, 2016 to 2025). Increased pressure within the pulmonary circulation due to lung or heart disorder. "PRKG1 deficiency can result in pulmonary hypertension via the activation of Rho A/Rho kinase signaling pathway." (PMID 35740428, 2022). "Biomarker genes for pulmonary hypertension included PRKG1, KCNMA1, FOXO1, and NOS3." (PMID 35740428, 2022).
Alzheimer disease (7 papers, 2015 to 2025). A progressive, neurodegenerative disease characterized by loss of function and death of nerve cells in several areas of the brain leading to loss of cognitive function such as memory and language. "A study with late-onset Alzheimer’s disease samples indicated a significant association of rs10824310 in the PRKG1 gene." (PMID 40170191, 2025).
diabetes (7 papers, 2006 to 2025). "Thus, the decreased IL‐2 levels, potentially driven by changes in PRKG1, seen in individuals with diabetes and COVID‐19 may impair this immune mechanism, predisposing individuals with diabetes to worsened immune responses." (PMID 40476695, 2025). "Presently, however, no other literature exists regarding the remaining four critically differentially expressed genes, GRASP, MYZAP, PRKG1, and SMIM24, in diabetes patients." (PMID 40476695, 2025). "Several genes, including GRASP, KRT8, MYZAP, PRKG1, and SMIM24 were differentially expressed in the COVID versus no COVID and diabetes versus no diabetes subgroup analyses." (PMID 40476695, 2025).
Obesity (7 papers, 2012 to 2025). Accumulation of substantial excess body fat. "Our analysis suggested significant enrichment (corrected P‐value < 0.01) in various catalogs, including obesity‐related traits (e.g., GMDS, PRKG1, and BMP2), Height (e.g., IGF2BP3, BMP2, and BMP3), and Body mass index (e.g., BMP2)." (PMID 40167159, 2025).
myocardial infarction (6 papers, 2013 to 2025). Gross necrosis of the myocardium, as a result of interruption of the blood supply to the area, as in coronary thrombosis. "In addition, genome-wide association studies (GWAS) have associated variants in VEGFA with coronary heart disease and myocardial infarction, and variants in other gene targets of miR-20a-5p, CDKN1A (also a common gene target of miR-181a-5p) and PRKG1 with stroke." (PMID 36613546, 2022).
thoracic aortic aneurysm (6 papers, 2018 to 2024). An aneurysm formed in the wall of the proximal portion of the descending aorta proceeding from the arch of the aorta. "WES identified recurrent gain-of-function mutations in PRKG1 as causative for thoracic aortic aneurysms and acute aortic dissections, meanwhile MAT2A, LOX, and FOXE3 have been suggested as predisposing genes." (PMID 35892496, 2022). "The Ser/Thr kinase encoded by the PRKG1 gene has a crucial function in smooth muscle activity, and has been associated with thoracic aortic aneurysm in humans." (PMID 31783652, 2019). "People heterozygous for an activating mutation in protein kinase G1 (PRKG1, p.Arg177Gln) develop thoracic aortic aneurysms and dissections (TAAD) as young adults." (PMID 31387997, 2019). "In addition, mutations in PRKG1 can cause thoracic aortic aneurysms and acute aortic dissections, while mutations in GUCY1A3 are associated with an autosomal-recessive disease leading to severe moyamoya and early-onset achalasia." (PMID 30001348, 2018). "The age at dissection varied according to the underlying NS‐TAD form, with a mean age of presentation of 32 years for the familial thoracic aortic aneurysm and dissection forms associated with the mutations of the PRKG1 gene and of 54 years for those associated with the mutation of the MYLK gene." (PMID 30371227, 2018).
schizophrenia (5 papers, 2013 to 2025). A major psychotic disorder characterized by abnormalities in the perception or expression of reality. "PRKG1 has previously shown its association with schizophrenia with the 21st most significant SNP in the CATIE GWAS." (PMID 23922650, 2013). "PRKG1 was reported to be significantly associated with schizophrenia." (PMID 29257106, 2017). "Of the 10 potential candidate genes, 3 genes (Atad1, Cdc37l1, and Prkg1) were differentially expressed between schizophrenia patients and the control group." (PMID 41153356, 2025). "PRKG1 also interacts with RGS2 and GABRR1, which have shown modest association with schizophrenia symptoms and schizoaffective disorder, respectively." (PMID 23922650, 2013). "Finally, using an RNA-seq dataset, we found differential expression of ATAD1, including two other candidates, CDC37L1 and PRKG1, between schizophrenia and control groups, suggesting that examination of co-regulation of Atad1 and other “players” is warranted." (PMID 41153356, 2025). "Multiple differentially expressed genes (KCNIP4, GRM3, PRKG1, NPY for inh-C, and TRPC3 for inh-CCK) were related to glutamate reception and calcium channel activity, indicating these processes are altered within inhibitory midbrain neurons in schizophrenia." (PMID 39397771, 2025).
Aortic dissection (4 papers, 2018 to 2024). Aortic dissection refers to a tear in the intimal layer of the aorta causing a separation between the intima and the medial layers of the aorta. "Of the 31 family members carrying the PRKG1 gene, 63% presented with an acute aortic dissection." (PMID 40337343, 2024).
COVID-19 (4 papers, 2022 to 2024). A disease caused by infection with severe acute respiratory syndrome coronavirus 2. "Antibodies cross-reacting with PRKG1 and tropomyosin may cause known COVID-19 complications such as blood-clotting disorders and cardiac disease, respectively." (PMID 35891400, 2022). "Some genes that may be related to severe COVID-19 pathophysiology and are good candidates for experimental investigation include PRKG1, ACE, CFB, CRP, CTNNB1, EGFR, and VEGFA." (PMID 35794133, 2022).
gastric cancer (4 papers, 2021 to 2025). A primary or metastatic malignant neoplasm involving the stomach. "further demonstrated that PRKG1 inhibits the epidermal growth factor‐induced MAPK/ERK signalling pathway, reducing the invasive and proliferative capabilities of gastric cancer cells, suggesting PRKG1 as a potential therapeutic target." (PMID 39783847, 2025).
Achalasia (3 papers, 2018 to 2024). A disorder of esophageal motility characterized by the inability of the lower esophageal sphincter to relax during swallowing and by inadequate or lacking peristalsis in the lower half of the body of the esophagus. "First, the evaluation of the molecular mechanism of miR-200c-3p-mediated PRKG1 in vivo and second, the pathogenic effect of miR-200c-3p on achalasia." (PMID 36614110, 2022). "This functional study provides evidence that miR-200c-3p directly regulates PRKG1 and suggests the involvement of NO/cGMP/PKG signaling in the pathogenesis of achalasia." (PMID 36614110, 2022). "miR-200c-3p-mediated PRKG1 regulation could induce an achalasia-like phenotype in the smooth muscle cells through suppression of the NO/cGMP pathway." (PMID 36614110, 2022). "We hypothesized that miR-200c-3p-mediated PRKG1 expression could play a crucial role in the etiopathogenesis of achalasia." (PMID 36614110, 2022). "Our study provides, for the first time, functional evidence about the PRKG1 gene as a direct target and SULF1 and SYDE1 as potential indirect substrates of miR-200c-3p and suggests the involvement of NO/cGMP/PKG signaling in the pathogenesis of achalasia." (PMID 36614110, 2022).
glioblastoma (3 papers, 2016 to 2023). The most malignant astrocytic tumor (WHO grade IV). "The effect was greater for the sphere phenotype, and activation of PRKG1 resulted in reduced cell viability in both patient derived glioblastoma cell cultures." (PMID 27564115, 2016). "For the adherent phenotype, activation of PRKG1 reduced cell viability compared to control in both patient derived glioblastoma cell cultures." (PMID 27564115, 2016). "PPI and gene ontology networks examined suggest the existence of further targets to be explored for the treatment of glioblastoma, such as PRKG1, CFTR, PLCB1, and TBX2." (PMID 27564115, 2016). "PRKG1, known to induce apoptosis when activated, is increased in all patient derived glioblastoma spheres." (PMID 27564115, 2016). "PRKG1 appears to be a novel therapeutic phenotype-specific drug for the treatment of glioblastoma." (PMID 27564115, 2016). "Analysis of the networks formed by HF2303 or IN2045 demonstrated a close association of PRKG1 with CFTR, two proteins not yet linked to glioblastoma biology." (PMID 27564115, 2016).